CASP8 (caspase 8)
Diseases named in the same sentence as CASP8 in open-access papers (continued):
Sharing a sentence is not in itself a finding about the gene and the disease.
tumor (continued). "Nevertheless, TRAIL dosage (100 μg) in this therapy was too low to synergize with IVM and/or CQ to reduce tumor growth and activate death receptor signaling (in terms of procaspase-8/cleaved caspase-8 ratio) as potent as those in vitro, especially when tumors were big." (PMID 30742128, 2019). "In addition, the present study provides the first evidence that the percentage of CASP8 neurons in the MPs close to tumor invasion was significantly lower compared to unchanged part of the stomach wall." (PMID 30019295, 2018). "Similarly, DDP is widely known to mainly activate caspase-8 and -3 to induce the extrinsic apoptotic pathway in tumor cells and OLE was demonstrated to induce both apoptotic pathways." (PMID 30267330, 2018). "As an example, the identification of Caspase-8 as a novel modulator of tumor microenvironment, suggests that the modulation of Caspase-8 may affect chemotherapy sensitivity not only by impinging on the apoptotic response but also through additional pathways." (PMID 30501030, 2018). "Furthermore, the ATF4/CHOP axis in tumor-infiltrating MDSCs accelerates apoptosis through death receptor 5 (DR5) and caspase-8 activation, suggesting that UPR activation plays a key role in modulating tumor-associated immune responses." (PMID 30282948, 2018). "Moreover, percentage of GAL-immunoreactive neurons devoid of CASP8 was significantly higher only in vicinity of tumor invasion." (PMID 30019295, 2018). "To translate our in vitro findings into an in vivo model of primary tumor growth we first knocked-down stably caspase-8 expression in p95HER2/611CTF-overexpressing breast epithelial cells with shRNA by lentiviral infection and determined the apoptotic response of these cells to metabolic stress." (PMID 29212182, 2017). "CDKN2A (9%), FAT1 (23%), SMAD4 (11%), and CASP8 (13%) mutations were only present in HPV-negative HNSCC cell lines, which was consistent with the HNSCC TCGA data, where each of these mutations occurred in only 1 HPV-positive HNSCC patient tumor." (PMID 29156801, 2017). "The pattern of mutations in across these genes was generally consistent with loss of function (data not shown), although some CASP8 mutations have been shown to increase nuclear factor kappa B signaling in tumor models." (PMID 28749946, 2017). "For example, TFs, such as ASH1L, CFLAR, HMGB3, ZNF160 and MATR3, displayed opposite behaviors on some cytokines; inflammatory factors; nuclear and tumor factors, such as IL-2, IL-6, NF-κB, and Irf3; immunogenic nucleic acids; papillomavirus E7/E6; caspase-3/caspase-8; Toll-like receptor; and so on." (PMID 28719625, 2017). "CASP8, another member of the caspase family, is a tumour suppressor in breast cancer." (PMID 29089486, 2017). "In addition, co-treatment with TRAIL and a cFLIP-targeting siRNA has been recently reported to enhance the apoptosis of TRAIL-resistant tumor cells via caspase-8 activation." (PMID 28086218, 2017). "On the other hand, the minor expansion of the osteolytic lesions in tibiae of mice treated with those cells confirmed the capacity of our vector to trigger the secretion of the apoptosis inducer in the presence of MM cells resulting in tumor cell death by activation of caspase-8." (PMID 28962646, 2017). "In addition, in vivo experiments demonstrate a key role of caspase-8 in the prevention of p95HER2/611CTF-mediated tumor formation." (PMID 29212182, 2017). "We found that in the lines, as in primary tumours, inactivating mutations in CASP8 did not result in a reduction in CASP8 expression, whereas FAT1 mutation did correlate with reduced mRNA levels." (PMID 27693639, 2016). "The effects of disturbance of CASP8 pathways might, therefore, vary between different tissue and tumour types." (PMID 26740556, 2016). "These similar findings suggest that ixazomib and bortezomib may both initiate tumor cell death through activation of the extrinsic pathway of apoptosis via FADD-induced caspase-8 activation." (PMID 27783987, 2016).
tumor (continued). "Because HDAC inhibitors are known to preferentially induce caspase-8 activation to contribute to tumor cell death, we asked whether panobinostat induces caspase-8-dependent Sp1 protein degradation in MM cells." (PMID 27738323, 2016). "One predictable outcome of reduced caspase-8 signalling might be a failure of incipient tumour cells to undergo apoptosis." (PMID 25855136, 2015). "It is therefore possible that an inhibition of caspase-8 signalling in BCC risk allele carriers could act to promote necrosis and inflammation, thereby generating a tumour-promoting environment within the epidermis." (PMID 25855136, 2015). "We observed a strong association between somatic variations in some key genes with one or more risk habits; for example,CDKN2A andPIK3CA with smoking;CASP8 with consuming alcohol and chewing tobacco;RASA1 with chewing and tumor stage, and HPV infection, along withDMD andPIK3CA." (PMID 26834999, 2015). "Since caspase 8 acts to up-regulate levels of caspase 3, these results are in line with the observed decrease in the conversion of pro-caspase 3 to caspase 3 upon incubation of tumor cells with hCG." (PMID 26608647, 2015). "In addition to these pro-tumor roles of caspase-8, cells with impaired apoptosis despite displaying continued caspase activation have been shown to secrete mitogenic signals in a manner which is dependent on the catalytic activity of caspases." (PMID 26507126, 2015). "Further, there are recent evidences that caspase-8 could exert a pro-tumor role by inducing cell motility, adhesion and metastasis." (PMID 26507126, 2015). "Active form of caspase-3 and caspase-8 were observed in the tumor." (PMID 25797270, 2015). "Although slight decreases in the expression levels of procaspase-9 and PARP were detected in the group treated with cryoablated tumor extracts, this might be a consequence of the activation of caspase-8." (PMID 24818132, 2014). "Additionally, IL8 decreased sensitivity of tumor cells to caspase 8-mediated, TRAIL-induced apoptosis via increased expression of c-FLIPL and c-FLIPS which are two isoforms of the endogenous caspase 8 inhibitor." (PMID 24755559, 2014). "We measured caspase 8 mRNA expression in two independent cohorts of NB tumor samples." (PMID 25502557, 2014). "Many of these additional mutated genes are pro-apoptotic, such as CASP8, BID, and SIAH1, suggesting that for relapse tumors to develop, tumor cells might need to acquire extra survival advantages." (PMID 25123191, 2014). "Furthermore, the prognostic role of nuclear localisation of caspase-8 needs to be confirmed in larger trials and other tumor entities." (PMID 24209510, 2013). "The Fas/FasL-activated caspase-8/caspase-3 pathway may be involved in tumor cell response to cisplatin." (PMID 23817665, 2013). "Multivariate Cox regression analysis confirmed cytosolic caspase-8 to be a survival predictor independent from tumor grading [G3 versus G1/2: HR = 2.28 (95% CI: 1.14-4.55), p = 0.0196 and cytosolic caspase-8 <2.8 versus ≥2.8: HR = 2.39 (95% CI: 1.16-4.92), p = 0.0182]." (PMID 24209510, 2013). "However, high cytosolic caspase-8 expression in tumor tissue (IRS ≥2.8) significantly correlated with better survival." (PMID 24209510, 2013). "Further analysis of tumor cell lysates revealed that protein expression of cleaved caspase 8, a molecule involved in the extrinsic pathway downstream of activated caspase 10 was significantly increased in tumor xenografts treated with simvastatin, compared to saline treated controls (p<0.01)." (PMID 22974127, 2012). "The decrease in tumor size seen with PQ treatment may be attributed to an increase in apoptosis as the result of an up-regulation of caspase-3, caspase-8, and caspase-9." (PMID 23028705, 2012).
tumor (continued). "To study the effects of pardaxin on tumor functions, we performed a real-time RT-PCR analysis of caspase-3, caspase-7, caspase-8, caspase-9, Bax, Bcl-2, STAT2, ATF3, STAT3, SOCS3, IL-2, cathelicidin, TNF-α, MyD88, NF-κB1, p65, IFN-β1, IFN-γ, IL-1β, IL-6, IL-7r, and IL-10." (PMID 23015777, 2012). "The increase of caspase-8 activation suggests that C7a treatment of tumor cells may also affect a receptor-mediated reaction in addition to the intrinsic pathway of cell apoptosis." (PMID 21756336, 2011). "Although caspase-8 mutation is rare in HNSCC, the understanding of the molecular mechanisms underlying chemoresistance in tumor cells may help to design new strategies for chemotherapy." (PMID 21801448, 2011). "Likewise, overexpression of TRAIL-R4 protects tumor cells against TRAIL-induced cell death by regulating caspase-8 activation at the DISC level." (PMID 21625476, 2011). "These isoforms of c-FLIP, although generally expressed at a lower level compared to caspase-8 in most tumor cell lines, are recruited within the DISC together with caspase-8 where they inhibit the activation of the initiator caspases, impairing apoptotic triggering." (PMID 21756247, 2011). "Similar to DR5, an analysis of the correlation between caspase-8 expression and the clinical parameters including gender, age at diagnosis, smoking status, tumor site, tumor size, tumor stage, nodal status, histologic grade, overall survival and disease-free survival was performed." (PMID 20808443, 2010). "Some tumor stromal cells including fibroblasts and immune cells were positive for caspase-8." (PMID 20808443, 2010). "Caspase-8-dependent apoptosis may be triggered by cell surface receptors belonging to the tumor gene superfamily, including CD95 (or Fas), TNF receptor-1 (TNFR1), and TNF-related apoptosis-inducing ligand (TRAIL)." (PMID 20089176, 2010). "Multivariable analysis adjusting for age, tumor stage, gender, histologic grade, smoking, chemo and/or radiation therapy, and tumor site showed that high caspase-8 (greater than mean) in the Tu−met group was also significantly associated with better overall survival (P = 0.0026, HR = 0.255)." (PMID 20808443, 2010). "Despite the hypomethylation state of DR4 receptor and hypermethylation state of anti-apoptotic decoy receptors (DCR1 and DCR2), we propose that the final outcome in tumor pathogenesis depends on downstream signal transduction molecules, such as CASP8, FLIP and CYCS in established tumors." (PMID 21092294, 2010). "A wealth of data has been published concerning caspase-8 as potential tumor suppressor." (PMID 24281211, 2010). "There is experimental evidence from transgenic mice that certain initiator caspases, such as caspase-8 and -2, might act as tumor suppressors." (PMID 24281211, 2010). "In addition, hTERT promoter has been used to target other tumor killing factors, such as caspase 8, TRAIL and Bax, and subsequently induces tumor specific apoptosis and enhances the sensitivity of tumor cells to GCV without adverse effect." (PMID 20626878, 2010). "However, in tumor cells, over-expression of cFLIP inhibited the activation of the caspase-8 signal transduction pathway and cell apoptosis." (PMID 19476635, 2009). "Since caspase-8 maturation occurs concomitant with the accumulation of DEDs, DED accumulation may act to oppose NF-κB signaling, functioning as a tumor suppressor via their microtubule-associated function." (PMID 19924290, 2009). "To examine whether Vpr and C81 target mitochondria in tumor cells, we measured caspase-8 and caspase-9 activity." (PMID 19674438, 2009). "Furthermore, Bid is constitutively expressed in many tumours and is cleaved by several stress-activated proteases other than caspase-8 or -10." (PMID 18665234, 2008). "In addition, there was significant induction of caspase-8 activity, and a much smaller induction of caspase-9 activity, indicating that EphB4 protects tumour cells from the extrinsic, membrane-originating apoptotic pathways." (PMID 17353927, 2007).
tumor (continued). "Available evidence suggests that IRF-1 may function as a tumor-suppressor gene and might induce apoptosis mediated via up-regulation of caspase 8, a key mediator frequently inactivated by epigenetic silencing in many tumors by gene hypermethylation." (PMID 17319941, 2007). "HGS-ETR1 reduced the viability of multiple types of tumour cells in vitro, and induced activation of caspase 8, Bid, caspase 9, caspase 3, and cleavage of PARP, indicating activation of TRAIL-R1 alone was sufficient to induce both extrinsic and intrinsic apoptotic pathways." (PMID 15846298, 2005). "However, specific gene mutations have not been defined, although we did identify RASSF1A methylation in 55% of NBs and that CASP8 methylation occurs in ∼50% of tumours." (PMID 14735202, 2004). "Consequently, deactivating caspase-8 could significantly enhance tumor cell necroptosis after radiotherapy, offering a potential approach for in-situ vaccination through boosting tumor cell immunogenicity and antigenicity." (PMID 41041050, 2025). "This information would provide us with supplementary valuable information about the modified factors by Caspase-8, which could be used as new pharmacological targets to reduce the tumor-supportive properties of the tumor microenvironment and to improve the tumor response to classical therapies." (PMID 40674382, 2025). "In addition to the endogenous pathways, heat therapy also affects the exogenous apoptotic pathways by activating death receptors on the cell surface, and in some tumor cells, heat therapy induces apoptosis through Fas signaling and can activate both Caspase-3 and Caspase-8." (PMID 39027362, 2024). "While PANoptosis plays a critical role in tumor suppression by stimulating antitumor immunity, some studies have reported that elevated caspase-8 can promote tumor growth and progression, suggesting that PANoptosis may also facilitate tumor development under certain conditions." (PMID 38877579, 2024). "Similarly, BCL2L1 expression was significantly (p < 0.001) higher in the tumor than in the normal tissue in UCEC, COAD, and STAD patients, whereas CASP8 was significantly (p < 0.001) higher in the normal tissue than in the tumor tissue (either p < 0.05 or p < 0.001) in LUSC." (PMID 38542508, 2024). "Hence, caspase-8 can act as both a promoter and inhibitor of tumor growth." (PMID 39625520, 2024). "The combination of birinapant and irradiation or irradiation alone also significantly inhibited tumor growth in UM-SCC-11B xenografts overexpressing FADD and BIRC2, but not in UM-SCC-1 xenografts showing weaker growth and FADD/BIRC2 copy expression and heterozygous CASP8 mutation." (PMID 39458950, 2024). "Therefore, it may be possible to inhibit CASP8 expression to enhance T‐cell activation and suppress tumor formation." (PMID 36533709, 2023). "Moreover, CASP8 expression was evaluated in 62 ESCA tumor tissues and 18 healthy tissues by IHC." (PMID 36533709, 2023). "Moreover, studies have revealed that α-KG can induce pyroptosis to inhibit tumor growth by activating caspase-8 and cleaving gasdermin C, suggesting that caspase-8-mediated pyroptosis may enhance the efficacy of antitumor drugs." (PMID 37214439, 2023). "Thus, the tumor promoting the function of caspase-8 may be regulated by its localization in the cell." (PMID 35741016, 2022). "Besides, animal experiments in vivo via oral administration of PEG/ZIF-8@HF further confirms that PEG/ZIF-8@HF shows anti-tumor effect by up-regulating the pro-apoptotic proteins caspase-3 and caspase-8, and down-regulating the migration-promoting invasion protein MMP-9." (PMID 35373691, 2022). "However, it remains unknown if cFLIP could also play a role in the regulation of TRAIL-R2/DR5-dependent caspase-8 activation and apoptosis in tumor cells undergoing ER stress." (PMID 35115486, 2022).
tumor (continued). "Hence, by maintaining the FLIPL levels in cell cycle-arrested tumor cells, tumor spheroids might acquire resistance to ER stress-induced caspase-8 activation and apoptosis despite the upregulation of TRAILR2/DR5." (PMID 36012252, 2022). "The mutation frequencies of several tumor-suppressor genes including FAT1, CDKN2A, FGFR3, and CASP8 were lower in the HPV-positive group of HNSC, and even the mutation frequencies of FAT1, CDKN2A, and CASP8 were 0, indicating that the biological processes regulated by these genes were not disrupted." (PMID 35392231, 2022). "Interestingly, both caspase-2 and caspase-8 have been shown to play a tumor-promoting role." (PMID 35741016, 2022). "However, the induction of autophagy also facilitates the activation of apoptosis by generating a platform for activating caspase-8 or depleting endogenous inhibitors of this cell death pathway, as observed on tumor cells exposed to Bortezomib, which showed apoptosis via caspase-3 activation." (PMID 34679068, 2021). "Drug-induced caspase-8 expression could be an attractive therapeutic opportunity in tumors in which the downregulation of caspase-8 leads to tumor progression, immunoescape, and increased secretion of immunosuppressive and tumor-supportive proteins into the TME." (PMID 33026575, 2021). "Caspase-8 may therefore be the link in the crosstalk between the tumor and the TME." (PMID 33026575, 2021). "Furthermore, immunosuppressive molecules B7-H3, CD86, and CD38 as well as necroptosome components cleaved caspase-8 and RIP3 (also known as RIPK3) were relatively underexpressed in ASPcKO tumors suggesting less immune surveillance in the tumor microenvironment with Pten loss." (PMID 34535684, 2021). "Interestingly, except HNSCC, there are no other tumour types with >10% incidence of CASP8 mutations." (PMID 33602906, 2021). "Notably, in E-SOBP cells, we observed upregulation CASP8 molecular switch for apoptotic pathway, the anti-proliferative tumor regulator CDKN1C, and tumor suppressor and Ras Suppressor Protein 1, which is also a strong tumor suppressor gene in E-SOBP treated cells." (PMID 34885223, 2021). "This extract acted by the induction of apoptosis through elevating the expression of proapoptotic factor Bim and caspase-8 and -3 as well as the downregulation of Bcl-2 expression, suggesting the modulation of both intrinsic and extrinsic pathways due to the exposure of the tumor to the extract." (PMID 33916780, 2021). "This would provide us with more valuable information about the clinical relevance of caspase-8 and the modified factors by caspase-8, which could be used as new drug targets to reduce the tumor-supportive properties of the TME and to improve the tumor response to the classical therapies." (PMID 33026575, 2021). "Caspase-8 is placed at central nodes of multiple signal pathways, regulating not only the cell cycle but also the invasive and metastatic cell behavior, the immune cell homeostasis and cytokine production, which are the two major components of the tumor microenvironment (TME)." (PMID 33026575, 2021). "The authors found that ASC ablation in murine tumor cell lines in vitro enhanced cellular motility and invadopodia formation through cytoskeletal reorganization, as well as Src accessibility to caspase-8 for ensuing phosphorylation (p-caspase-8 is pro-metastatic) and cellular migration." (PMID 32117971, 2020). "To further investigate the role of p62/SQSTM1 in the sensitization to TRAIL observed in GBM cells after PIM disabling, we performed co-immunoprecipitation assays to test whether p62/SQSTM1 interacts with caspase-8 upon TRAIL treatment as reported in other tumor cells." (PMID 30718520, 2019).